IL24 (interleukin 24)
Diseases named in the same sentence as IL24 in open-access papers (continued):
Sharing a sentence is not in itself a finding about the gene and the disease.
tumor (continued). "To further substantiate an activation of the apoptosis pathway, we analyzed the effect of B.breve-IL-24 on caspase-3 activation in tumor tissues." (PMID 35814447, 2022). "Based on these results, IL-24 can efficiently enhance the tumor regression potential of the E7 DNA vaccine, especially in the long term." (PMID 35752792, 2022). "From week 4 on, the tumor volume of the E7&IL-24 group followed a prominent regression trend so that the tumor size of this group on weeks 5 and 6 was considerably (P < 0.001) less than that of both E7 and IL-24 groups." (PMID 35752792, 2022). "Results showed higher tumors grew in the control group compared to B.breve-IL-24-treated mice, which suggests that the B.breve-IL-24 strain can inhibit tumor growth over time." (PMID 35814447, 2022). "The data suggest the synergistic effect of the E7 DNA vaccine on IL-24 engagement at the tumor site." (PMID 35752792, 2022). "These viruses have also been engineered to conditionally express a tumor suppressor gene, mda-7/IL-24, under control of a CMV promoter, referred to as a Cancer Terminator virus (CTV)." (PMID 35326649, 2022). "It was reported that IL-24 induces a positive anti-tumor effect by decreasing the activity of Tregs and increasing the activity of CD8+ T lymphocytes." (PMID 35752792, 2022). "OncoAd co-expressing hsa-miR-34a and interleukin-24 (IL-24) induced increased anti-tumour activity compared with OncoAd expressing hsa-miR-34a or IL-24 alone." (PMID 36138344, 2022). "Compared to parental MDA-7 (IL-24), M7S (IL-24S) was superior in promoting anti-tumor and bystander effects leading to improved outcomes in multiple cancer xenograft models." (PMID 35402258, 2022). "The formalin-fixed, paraffin-embedded tumor tissue was prepared, and stained tissues were visualized after treatment with the anti-IL-24 antibody." (PMID 35752792, 2022). "Smaller tumor size was detected in E7&IL-24 (P < 0.001), E7 (P < 0.01), and IL-24 (P < 0.05) groups when coupled with anti-IL-10 compared with isotype analogs." (PMID 35752792, 2022). "IL-24 was shown to display anti-tumor effects and inhibit hepatocellular carcinoma metastasis, but its role in regulating liver inflammation and fibrosis is yet to be well characterized." (PMID 35054813, 2022). "We found that WT1 overexpression induces G2/M checkpoint arrest through the upregulation of IL-24, thereby inhibiting tumor cell proliferation." (PMID 35915803, 2022). "IL-24 is a unique tumor-suppressing cytokine, which can inhibit tumor growth, invasion, metastasis, and angiogenesis and induce apoptosis through autocrine-paracrine regulation." (PMID 35915803, 2022). "IL-24 shows low expression in many tumor cells, and the mechanism regulating its expression is still unclear." (PMID 35915803, 2022). "This study demonstrated that the expression of tumor-suppressing gene IL-24 mediated by vaccinia virus strain VG9 (VG9-IL-24) exhibited obvious antitumor effects on HCC both in vitro and in vivo." (PMID 35292065, 2022). "Ad-IL-24 induced G2/M cell-cycle arrest, apoptosis and tumor suppression of SGC7901/CDDP cells in vitro and in vivo." (PMID 35884907, 2022). "Nevertheless, the average tumor size (including slower tumor growth rate) in B. breve-IL24 was smaller compared with the B. breve-GFP group." (PMID 35814447, 2022). "It seems that E7&IL-24 co-administration can develop strong specific CTL responses among tumor-bearing mice." (PMID 35752792, 2022). "Examination using immunohistochemical (IHC) staining for the IL-24 protein revealed that IL-24 was expressed significantly higher in tumor tissue from the VV-IL-24 plus luteolin combination treatment group than in the other groups." (PMID 36146619, 2022).
tumor (continued). "Another member of the IL-10 family, IL-24, is also named MDA-7, which takes part in varieties of physiological activities under normal condition and has been emerged as an anti-tumor factor in multiple cancers." (PMID 36531027, 2022). "The traditional delivery of IL-24 by liposomes or replication-defective adenovirus cannot target tumor cells, which limits its value on cancer gene therapy." (PMID 35292065, 2022). "Given these scenarios, a recombinant vaccinia virus co-expressing GM-CSF and IL-24 has shown stronger anti-tumor activity than a virus carrying either GM-CSF or IL-24 alone." (PMID 35371972, 2022). "This study focused on examining the effect of the E7 DNA vaccine, IL-24, and E7&IL-24 on the tumor progression in TC-1 tumor-bearing C57BL/6 mice." (PMID 35752792, 2022). "In order to evaluate both the tumor suppressive effects of MDA-7/IL-24 as well as the “bystander” anti-tumor effect of MDA-7/IL-24, at least 50% of the tumors formed were treated." (PMID 33670594, 2021). "Another valuable finding from our studies was that estrogen also upregulated a tumor-suppressor gene, IL-24, only in GS3." (PMID 34944995, 2021). "TRAIL and IL-24 can interact and promote each other, further inducing substantial tumor apoptosis by activating intracellular tumor-killing mechanisms." (PMID 34901031, 2021). "Conversely, we observed that Hiltonol was more effective in elevating tumor suppressor, IL-24, in A549 and H292 cells (green boxes)." (PMID 33562773, 2021). "mda-7/IL-24 has well-established tumor-suppressor and apoptosis-promoting properties in a broad spectrum of human cancer cells." (PMID 33670594, 2021). "The molecular mechanism by which mda-7/IL-24 induces apoptosis is diverse involving different pathways in specific tumor contexts." (PMID 33670594, 2021). "Epigenetic processes are important modulators of the transcriptional regulation of tumor promoting and tumor suppressor genes, including mda-7/IL-24 transcriptional control." (PMID 35008495, 2021). "Different cohorts of Hi-Myc mice were treated with tumor-sensitized T cells that were engineered to produce human MDA-7/IL-24." (PMID 35008495, 2021). "IL-24 is an important immune mediator and a cancer suppressor that can specifically inhibit the growth of tumor cells and induce cancer cell apoptosis." (PMID 34563270, 2021). "Estrogen increased the percentage of cells expressing IL-24, associated with the estrogen-dependent inhibition of GS3 tumor growth." (PMID 34944995, 2021). "Altogether, these findings suggest that MDA-7/IL-24-engineered T cells exhibit superior anticancer activity by offsetting multiple immune limiting factors in the tumor microenvironment and targeting cancer cells beyond an antigen-specific fashion." (PMID 35008495, 2021). "As a conceptual advancement, our results reveal potential interactions between ESR1+ and ESR1– cells in both estrogen-stimulated and -suppressed ER+ tumors, as well as a potential tumor-suppressor role of IL-24." (PMID 34944995, 2021). "Nevertheless, a preclinical study indicated a benefit from Ad-IL-24 and erlotinib in terms of tumor growth inhibition and induction of apoptosis through Apaf-1 and AKT signaling pathway inhibition." (PMID 33918490, 2021). "Accordingly, studies have focused on improving the delivery of mda-7/IL-24 to tumor cells and defining ways to enhance anti-cancer effects." (PMID 35008495, 2021). "The coexpression of the ING4 and IL-24 double genes can selectively inhibit tumor angiogenesis and the growth of tumor cells through pathways both inside and outside of the cells." (PMID 34685354, 2021). "The strong expression of IL‐24 induces the promotion of tumor cell apoptosis which inhibits tumor growth, angiogenesis, or metastasis and even enhances immunoregulation." (PMID 33274495, 2021).
tumor (continued). "The tumor lesions received INGN 241 (Ad.5-mda-7) injections showed high levels of MDA-7/IL-24 protein expression, which correlated well with the apoptotic activity as evidenced by TUNEL assay." (PMID 35008495, 2021). "Immunohistochemical (IHC) staining demonstrated that after the treatment with the combination of VV‐IL‐24 and luteolin, the IL‐24 protein was expressed in tumor tissue at a markedly higher level than in the other groups." (PMID 33274495, 2021). "The efficacy of MDA-7/IL-24 as a cancer therapeutic has been established in pre-clinical studies using multiple tumor models, including nude mice, syngeneic mice and transgenic animals." (PMID 35008495, 2021). "At the supraphysiological level, IL24 mRNA significantly inhibits tumor growth, invasion, metastasis, and angiogenesis." (PMID 33014054, 2020). "In our previous investigation, we have confirmed that the exogenous IL-24 gene harbored in ZD55-IL-24 viral genome played an important role in immunocompromised mouse–human tumor xenograft models." (PMID 33257647, 2020). "Adenovirus (Ad)-mediated gene therapies using tumor suppressor genes such as interleukin 24 (IL24) suppresses the growth of NSCLC cells." (PMID 32357493, 2020). "A study of Bifidobacterium as a carrier of the IL24 mRNA to treat HNSCC in mice showed that the recombinant strain Bifidobacterium breve-IL24 had a stronger ability to inhibit tumor growth and induce tumor cell apoptosis." (PMID 33014054, 2020). "Other studies have shown that IL24 mRNA can enhance the immunogenicity of tumor cells through upregulation of costimulatory molecules, such as CD80 and CD86." (PMID 33014054, 2020). "IL24 has been reported to play vital roles in the inhibition of tumor growth and induction of tumor cell apoptosis in HNSCC cells." (PMID 33014054, 2020). "Similarity the beta glucan anti tumor activity, Interleukin-24(IL24) has been suggested as an effective anti-cancer agent." (PMID 32212815, 2020). "In this study, we injected iMSCs and IL-24-iMSCs into tumor-bearing mice by retro-orbital intravenous injection." (PMID 32015693, 2020). "The average weight of tumor tissue in control was 3.5-fold heavier than that of the IL-24-iMSCs group, 1.5-fold heavier than that of the iMSCs group." (PMID 32015693, 2020). "IL-24 belongs to the IL-10 family of cytokines that inhibits tumor cell growth and promotes tumor cell apoptosis by inhibiting angiogenesis, activating growth inhibition and DNA damage genes, and other signaling pathways, without harming healthy cells." (PMID 33031392, 2020). "Our results of combination regime showed its upregulation which is also lined with the tumor suppressor properties of IL-24." (PMID 33473259, 2020). "IL-24 is a tumor suppressor, which can promote apoptosis of tumor cells, inhibit angiogenesis, stimulate immune response and synergize with other drugs to enhance anti-tumor efficacy." (PMID 32015693, 2020). "Accordingly, we detected the production of IL24, which is a tumor-suppressing protein, and LIF, which inhibits cell differentiation." (PMID 33153019, 2020). "Traditional delivery of IL-24 by liposome or replication-defective adenovirus cannot target tumor cells, which limits its value on cancer gene therapy." (PMID 31956348, 2020). "Studies have shown that IL-24 can suppresses cell growth and induce apoptosis in a variety of tumor types 17, 30, 34-37." (PMID 31956348, 2020). "Immunohistochemical staining also confirmed that IL-24 was stably expressed in tumor tissue from VG9-IL-24-treated group." (PMID 31956348, 2020).
tumor (continued). "ZD55-IL-24, one of the most effective armed oncolytic viruses developed so far, was constructed by cloning the foreign antitumor gene mda-7/interleukin-24 (IL-24) into the tumor-targeting replicative viral vector ZD552,3." (PMID 33257647, 2020). "In contrast, the tumor necrosis area in the tumor sections injected with IL-24-iMSCs group was more than that in the iMSCs group." (PMID 32015693, 2020). "The in vitro study demonstrated that LX/IL-24 significantly enhanced tumor-specific cytotoxicity of splenocytes, as compared with parental virus." (PMID 31338417, 2019). "B16-LX/IL-24 immunization dramatically inhibited tumor growth, as compared with the B16-LX/RFP or B16 groups." (PMID 31338417, 2019). "No detectable cytotoxicity was observed when Hepa-1/6 cells were used as the targets, suggesting that the killing capacity of the splenocytes stimulated with LX/IL-24-infected tumor cells was tumor specific." (PMID 31338417, 2019). "Its expression decreased in poorly differentiated mouse tumors, paralleling the loss of RET/PTC3 expression along with tumor progression, thus supporting a role for IL-24 as a tumor suppressor factor." (PMID 31412566, 2019). "GLI1 inhibition and overexpression confirmed that IL-24-mediated anti-tumor effects involved the GLI-dependent pathway." (PMID 31783569, 2019). "To analyze the anti-tumor capability of the chimeric oncolytic adenoviruses with IL-24, we executed a cytotoxicity assay after infection with adenoviruses." (PMID 31145345, 2019). "CD8+ T cells from the LX/IL-24-infected tumor cell group exhibited significantly higher cytotoxicity against B16-F10 cells than other groups, whereas NK cells from all groups showed very low cytotoxicity against B16-F10 targets." (PMID 31338417, 2019). "IL-24 can also downregulate anti-apoptotic proteins such as Bcl-2 and Bcl-xL and produce of tumor-suppressing ceramides leading to endoplasmic reticulum stress, autophagy, and apoptosis in PCa." (PMID 30669553, 2019). "Although percentages of most immune cells were not affected after different vaccine treatments, a significantly higher proportion and number of CD4+ and CD8+ T cells were observed in TILs after treatment with LX/IL-24-modified tumor vaccines." (PMID 31338417, 2019). "LX/IL-24-modified tumor vaccine treatment also enhanced the function of the CD8+ T cells, as indicated by significantly higher proportion and numbers of IFN-γ-producing CD8+ T cells." (PMID 31338417, 2019). "Immunization with LX/IL-24-modified tumor cells further reduced tumor growth compared with the immunization with LX/RFP-modified tumor cells." (PMID 31338417, 2019). "Recent data from our group, as well as from others, have shown that exogenous IL-24 expression induces tumor cell killing and cell cycle arrest, leading to apoptosis in cancer cells." (PMID 31783569, 2019). "Splenocytes stimulated with LX/IL-24-infected B16-F10 exhibited significantly enhanced killing capacity against autologous tumor cells, as compared with irradiated B16-F10 or LX/RFP-infected B16-F10 stimulated splenocytes." (PMID 31338417, 2019). "Absolute numbers of TILs per tumor weight were significantly increased in the B16-LX/IL-24 group, as compared with other groups." (PMID 31338417, 2019). "Recently, our data suggested that tumor cells were cured by AdCN205-IL-24, an adenovirus serotype 5-based conditionally replicating adenovirus expressing IL-24 after infection." (PMID 31145345, 2019). "Interleukin-24 (IL-24) is a promising agent for cancer immunotherapy that induces apoptosis of tumor cells and enhances T cell activation and function." (PMID 31338417, 2019). "In vitro and in vivo studies were performed to examine the antitumor effects of LX/IL-24-modified tumor cells." (PMID 31338417, 2019). "Transduction of tumor or normal cells with the mda-7/IL-24 gene results in cancer-specific cell death." (PMID 31489119, 2019).
tumor (continued). "The results from all of these studies supported the tumor suppressor properties of IL-24 and resulted in the testing of adenovirus-mda-7 (INGN-241)-based cancer gene therapy in a phase I clinical trial for solid tumors." (PMID 31783569, 2019). "IL-24 mRNA relative level in tumor tissue was decreased when compared with non-tumor tissue (Mann-Whitney test, P < 0.0001)." (PMID 31921658, 2019). "In contrast, high concentration of IL-24 robustly increased both peripheral and tumor-infiltrating Th1 frequency (Tukey tests, P < 0.0001)." (PMID 31921658, 2019). "The percentages and absolute numbers per tumor weight of IFN-γ-producing CD8+ T cells were significantly enhanced in B16-LX/IL-24-treated group." (PMID 31338417, 2019). "The recombinant virus also efficiently expressed IL-24 on tumor cells, which makes it a suitable vector for ATV-NDV generation." (PMID 31338417, 2019). "Here, we found that antitumor effects were dramatically increased by tumor vaccine modified with NDV expressing IL-24." (PMID 31338417, 2019). "Although the percentages of IFN-γ-producing CD4+ T cells were slightly increased after B16-LX/IL-24 treatment, absolute numbers per tumor weight of these cells were significantly increased, compared with other groups." (PMID 31338417, 2019). "LX/IL-24-infected tumor cells exhibited strong antitumor effects both in prophylaxis and therapeutic models." (PMID 31338417, 2019). "Interleukin-24 (IL-24), a novel cytokine, has multiple mechanisms of anti-tumor effects, such as inducing tumor cells apoptosis, promoting “bystander” effects, and enhancing T cell responses." (PMID 31338417, 2019). "High concentration of IL-24 promoted both peripheral and tumor-infiltrating CD8+ T cells-induced cytotoxicity only in direct contact co-culture system, while IFN-γ production was elevated in both systems." (PMID 31921658, 2019). "The expression of IL-24 in tumor cells infected by recombinant virus was determined using B16-F10 and Hepa-1/6 cells." (PMID 31338417, 2019). "In conclusion, downregulation of Bcl-2 induced by miRNA-34a can overcome tumor cell resistance to IL-24 and enhanced its anti-tumor effect." (PMID 31781493, 2019). "IL-24 can be described as a “magic bullet,” including tumor-specific apoptosis induction, potent “bystander” effect, and ability to make cancer cells more sensitive to clinical therapeutic approaches, including radiation, chemical drugs, and immune antibodies." (PMID 31145345, 2019). "Taken together, our data well illustrates that LX/IL-24-modified tumor cells are a promising agent for cancer immunotherapy." (PMID 31338417, 2019). "The results showed that IL-24-iRGD induced apoptosis and inhibited tumor growth to a significantly greater extent, which had a higher tumor growth inhibition rate (59.1%) than the control treatment (26.2%)." (PMID 31346334, 2019). "In this analysis, an ING4/interleukin-24 (IL-24) bicistronic adenovirus (Ad-ING-IL-24) was constructed, since IL-24 has been proven to be a potent cytokine-tumor suppressor with broad-spectrum anticarcinogenic properties as well." (PMID 31390718, 2019). "CCK-8 results showed that 10 ng/ml of IL-24 stimulation slightly inhibited both peripheral and tumor-infiltrating CD4+ T cells proliferation (Tukey tests, P = 0.024 and P = 0.041, respectively)." (PMID 31921658, 2019). "Our qRT-PCR analysis demonstrated significant up-regulation of three tumor-promoting cytokines, Cxcl10, Ccl20, and Tnf and down-regulation of the tumor inhibitory cytokine Il24 in the MDA-F471 spheres relative to parental cells." (PMID 31001473, 2019). "IL-24 inhibits tumor cell growth by the induction of apoptosis and most attention has been given IL-24 as a cancer therapeutic." (PMID 29681905, 2018). "Interleukin 24 (IL-24) is a tumor-suppressing protein, which has the ability to inhibit angiogenesis, sensitize cancer cells to chemotherapy, and induce cancer cell-specific apoptosis." (PMID 29786657, 2018).